WBP1 (WW domain binding protein 1)
Synonyms: WBP-1
Tractability: No criterion of Open Targets' tractability assessment is met for any kind of drug.
Gene: Protein-coding gene on chromosome 2 (74,458,400 to 74,460,891, forward strand). Ensembl gene ENSG00000239779.
Subcellular location (Human Protein Atlas): Cytosol
Gene Ontology:
Molecular function: protein binding; WW domain binding
Genetic constraint (gnomAD): Loss-of-function variants: 23 observed, 27.28 expected, observed/expected ratio (o/e) 0.84, 90% interval 0.61 to 1.2. The upper end of that interval is the gene's LOEUF score, 1.2, which puts it in group 5 of 6, group 1 being the genes least tolerant of losing a copy. Missense variants: 330 observed, 347.5 expected, observed/expected ratio (o/e) 0.95, 90% interval 0.87 to 1.04. Synonymous variants: 122 observed, 131.82 expected, observed/expected ratio (o/e) 0.93, 90% interval 0.8 to 1.08.
Homologues: Orthologues: macaque WBP1 (96% identical), chimpanzee WBP1 (95% identical), rabbit WBP1 (90% identical), guinea pig WBP1 (89% identical), dog WBP1 (87% identical), pig WBP1 (86% identical), mouse Wbp1 (85% identical), rat Wbp1 (84% identical), tropical clawed frog wbp1 (45% identical), zebrafish si:ch73-290k24.6 (42% identical). Paralogues in human: WBP1L (37% identical), PRR7 (16% identical).
Diseases named in the same sentence as WBP1 in open-access papers:
WBP1 is named in the same sentence as 5 diseases in open-access papers, as found by Europe PMC text mining. Sharing a sentence is not in itself a finding about the gene and the disease. The quoted sentences say what the papers report.
breast carcinoma (1 paper, 2015). "The first example, WBP1 (WW domain binding protein 1), is a binding partner of WWOX tumor suppressor that is frequently mutated in breast cancer." (PMID 25749525, 2015).
pan (1 paper, 2023). "In pan cancer, NXF2B, MSLNL, PCGF1, INO80B-WBP1, LBX2-AS1, MRPL53, LBX2, TTC31, WDR54 and WBP1 were co-altered in the TLX2-altered group." (PMID 37758722, 2023).
cancer (2 papers, 2023 to 2025). A tumor composed of atypical neoplastic, often pleomorphic cells that invade other tissues. "While direct studies on WBP1 in cancer are limited, other WW domain-binding proteins, such as WWP1 and WBP2, have been demonstrated to play crucial roles in cancer metabolism." (PMID 40075333, 2025). "Our findings expand the current understanding of WBP1 function and suggest that it may play a broader role in cancer biology beyond its known involvement in cell cycle regulation and protein-protein interactions." (PMID 40075333, 2025). "However, it is important to note that additional experimental validation across different cancer types would be valuable to fully understand the extent of WBP1’s tissue-specific effects." (PMID 40075333, 2025). "While previous studies have suggested that mitochondrial dysfunction can promote ferroptosis and sensitize cancer cells to chemotherapy, our findings reveal that enhanced mitochondrial respiration, mediated by WBP1, can confer resistance to ferroptosis and chemotherapeutic agents in CRC cells." (PMID 40075333, 2025).
tumor (2 papers, 2015 to 2025). "First, our results are derived from in vitro experiments conducted on CRC cell lines, and further validation in animal models and primary tumor samples is necessary to confirm the role of WBP1 in chemoresistance and ferroptosis in vivo." (PMID 40075333, 2025). "This indicates that WBP1 plays a role in maintaining mitochondrial function, which is essential for its tumor-promoting effects in CRC cells." (PMID 40075333, 2025). "The establishment of xenograft models using WBP1 KO and overexpressing CRC cells would provide valuable insights into whether WBP1 modulation affects tumor growth, chemotherapy response, and ferroptosis sensitivity in vivo." (PMID 40075333, 2025). "As ferroptosis is a tumor-suppressive mechanism, we next calculated the ferroptosis score in CRC patients with low and high WBP1 expression based on a previously published method." (PMID 40075333, 2025).
WBP1 also shares sentences with these, for which no sentence is quoted: colorectal cancer (1 paper).